CXCR4 (C-X-C motif chemokine receptor 4)
Diseases named in the same sentence as CXCR4 in open-access papers (continued):
Sharing a sentence is not in itself a finding about the gene and the disease.
breast carcinoma (continued). "Both ANGPTL2 and CXCR4 expression levels were positively correlated with high MMP-13 expression in breast cancer patient specimens." (PMID 25773070, 2015). "Bone tissue-derived CXCL12 preferentially recruits breast cancer cells expressing CXCR4 to bone metastatic sites." (PMID 25773070, 2015). "Its upregulation is reported in skin, lung, pancreas, brain, and breast cancer, while, in pancreatic cancer and melanoma, CXCR4 is downregulated by promoter aberrant methylation." (PMID 25814785, 2015). "Recently, many studies have shown that the presence of the chemokine receptor CXCR4 is involved in many stages of tumorigenesis, as invasion and metastasis in several cancers, including breast cancer." (PMID 26528758, 2015). "CXCR4 positive breast cancer cells have been shown to metastasize to CXCL12 expressing organs as their first destination." (PMID 26055698, 2015). "Within this context, this review summarizes established studies involving expression of CXCR4 on breast cancer, focusing on its clinical significance." (PMID 26161302, 2015). "Before of analyse the potential effects of exosomes released by CXCR4-cells, we tested the effects of CXCR4 overexpression in the transfected breast cancer cell line." (PMID 26528758, 2015). "Elevated CXCR4 expression in breast cancer cells negatively correlates with overall survival and disease-free survival in breast cancer patients and is correlated with malignant breast stem cell activity." (PMID 26396176, 2015). "We demonstrated that TPD7 inhibited the breast cancer proliferation and down-regulated the CXCR4 expression on breast cancer cells both over-expressing and low-expressing HER2, an oncogene known to induce the chemokine receptor." (PMID 25753200, 2015). "They concluded that CXCR4 level is a predictive marker for patients with locally advanced breast cancer." (PMID 26576337, 2015). "Although this study did not determine distant metastasis and relapses after treatment, considerable knowledge regarding CXCR4 role in breast cancer metastasis to CXCL12 producing organs has emerged." (PMID 26576337, 2015). "Accumulating evidences suggested that breast cancer cells highly express active CCR7 and CXCR4 which are responsible for directing breast cancer cell migration and invasion, and it potentially leads to metastasis to liver, lung, bone marrow and lymph nodes." (PMID 26592552, 2015). "CXCR4 is over-expressed in many breast cancer cells (BCC), promoting cancer cell migration and invasion." (PMID 26231656, 2015). "Assuming therefore that GLI1 up-regulates a set of these CXCL12-related signaling components in breast cancer cells, we focused our study on CXCR4, CXCR7 and LCP1." (PMID 26413813, 2015). "Next, we examined co-dependent gene expression relationships between CXCR7 and CXCR4, since in breast cancer cells CXCR7 is known to regulate CXCL12-mediated cell motility by modulating CXCR4 expression." (PMID 25884570, 2015). "Next, we analyzed a potential relationship between ANGPTL2 and CXCR4 expression in primary tumors from 181 breast cancer patients." (PMID 25773070, 2015). "Recently, it has been demonstrated that IGF-1 cooperates with CXCR4 signaling to promote bone marrow metastasis of breast cancer, potentially one factor in the aggressive behavior of LumB tumors." (PMID 25632947, 2015). "Using anti-human CXCR4 monoclonal antibody, the immunoreactivity of membrane and cytoplasm was evaluated in breast cancer and correlated to sites of metastasis, particularly in CXCL12-producing organs." (PMID 26161302, 2015). "Intriguingly, CXCR4 co-expressed with CXCR7 enhances more CXCL12-induced migration and lung metastasis of breast cancer cells than the sole expression of CXCR4." (PMID 26413813, 2015). "Our study reveals that CXCR4-exosomes promote breast cancer cells proliferation, motility and metastasis, generating an enhanced tumorigenesis phenotype." (PMID 26528758, 2015).
breast carcinoma (continued). "For example, a low CXCR4 expression is detected in normal breast tissues, while a high expression is found in breast cancer tissues." (PMID 25846512, 2015). "In human breast cancer cells, nobiletin downregulated the constitutive expression of CXCR4 and MMP-9." (PMID 26131016, 2015). "Overall, our results showed that TPD7 exerted its anti-invasive effect through the down-regulation of CXCR4 expression and thus had the potential for the treatment of breast cancer." (PMID 25753200, 2015). "It was observed that breast cancer patients presented a higher CXCR4 mRNA relative expression (5.7 fold) than the mRNA from normal mammary gland." (PMID 26576337, 2015). "We then applied this finding to the dormancy of metastasized breast cancer cells and found dynamic changes of the expression level of CXCR4 in cancer cells along with the entrance and exit of cancer cell dormancy." (PMID 26083776, 2015). "Animal experiments also show that CXCR4 monoclonal antibody can inhibit lymph node metastasis of human breast cancer cells in nude mice." (PMID 25866764, 2015). "Inside this context, this review focused on reporting the importance of immunohistochemical expression of CXCR4 on breast cancer and its clinical significance." (PMID 26161302, 2015). "In this context, it has been reported that basal-like and HER2 enriched breast cancer subtypes express CXCR4 staining more often than the other subtypes." (PMID 26576337, 2015). "The CXCR4 signaling pathway facilitates breast cancer cell survival, proliferation, chemotaxis, invasion and adhesion." (PMID 27429863, 2015). "In this context, it was recently demonstrated that violacein reduces the production of CXCL12 and its interaction with CXCR4 in a model of human breast cancer through the inhibition of matrix metalloproteinase-2/9 activity." (PMID 25938431, 2015). "HER2 has been shown to induce the expression of CXCR4 in breast cancer cells 19, and it has been reported to regulate the expression of CXCR4 by stimulating CXCR4 translation and attenuating CXCR4 degradation." (PMID 25753200, 2015). "Previously, we and others demonstrated that CXCR4 surface expression is an independent prognostic factor for disease relapse and survival in breast cancer." (PMID 25544759, 2015). "It has been found that CXCR4 is required for breast cancer cell migration to other sites such as lung, bone, and lymph nodes, which express high levels of CXCL12 chemokine." (PMID 26161302, 2015). "Breast cancer cells overexpressing CXCR4 showed an increase in stemness-related markers, and in proliferation, migration and invasion capacities." (PMID 26528758, 2015). "It suggested that the chemokine CXCL12 and its sole ligand CXCR4 play important role in the malignance of breast cancer." (PMID 24810923, 2014). "The data also support the importance of the CXCR4/CXCL12 interaction in breast cancer metastasis, and further suggest that CXCR4 and CXCL12 are critical targets for tamoxifen and tranilast in combination or alone." (PMID 25237365, 2014). "Chemo-attraction by lung tissue extracts was abolished by CXCL12-neutralizing antibodies and by preincubation of breast cancer cells with CXCR4-blocking antibodies." (PMID 24390633, 2014). "Because the CXCL12-CXCR4 axis has significant function in breast cancer metastasis, it has also been targeted using CXCR4 antagonists." (PMID 25165728, 2014). "CXCR4 (C-X-C chemokine receptor 4) is highly expressed in breast cancer cells, and its ligand (C-X-C motif chemokine 12, CXCL12) is expressed in high levels in tissues invaded by metastasis." (PMID 25147739, 2014). "For this reason, CXCR4 has been found to be a prognostic marker in breast cancer, among other types of cancer." (PMID 24591761, 2014). "In this study, we investigated CXCR4 and CXCL12 expression in breast cancer and analyzed its association with clinicopathological factors by immunohistochemistry first." (PMID 24810923, 2014).
breast carcinoma (continued). "CAFs have been recognized as important regulators of tumor initiation by secreting CXCL12 to activate CXCR4 on breast cancer cells and stimulate tumor growth." (PMID 25110692, 2014). "Synergy between ErbB2 and CXCR4 seems to enhance the ability of breast cancer cells to metastasize to different sites." (PMID 25147739, 2014). "For example, an increase in CXCR4 surface expression in the two human breast cancer cell lines, MDA-MB-231 and MCF7, following exposure to hypoxia resulted in a significant increase in migration and invasion in response to SDF1-alpha in vitro." (PMID 24559071, 2014). "In conclusion, our current study demonstrated that the reduced miR-339-5p expression [our previous data] promoted BCL6 expression, which in turn induces cyclinD1 and CXCR4 expression for induction of breast cancer cell proliferation and invasion." (PMID 24917186, 2014). "The significance of the CXCL12/CXCR4 axis in breast cancer invasion and metastasis has been widely investigated." (PMID 24886617, 2014). "The CXCL12/CXCR4 axis plays major roles in breast cancer cell proliferation, migration, and invasion; thus, we analyzed the CXCL12-mediated growth and motility of MCF-7 cells overexpressing COUP-TFI." (PMID 24906407, 2014). "In conclusion, in this study shRNA eukaryotic expression vectors targeting CXCR4 were successfully constructed, and CXCR4-shRNA was found to significantly inhibit the proliferation, adhesion and migration of breast cancer cells in vitro." (PMID 25202367, 2014). "The mouse model of breast cancer was simulated by injecting MDA-MB-231BA-rfp cells transfected with CXCR4 RNAi into the tail vein." (PMID 24959222, 2014). "Similar CXCR4 tumor-promoting effects were observed in breast carcinoma, suggesting CXCL12 as possible autocrine/paracrine growth factor." (PMID 25484899, 2014). "Giα proteins have been implicated in breast cancer invasion in response to SDF1, which is the only ligand for GiαPCR CXCR4." (PMID 24521094, 2014). "Our results are consistent with a study of human breast cancer that also demonstrated the importance of CXCR4/SDF-1 signaling at the primary tumor microenvironment." (PMID 24728301, 2014). "The mechanism of breast cancer cell metastasis to the bone is complicated, however, the CXCR4/stromal cell-derived factor-1 axis has a vital regulatory function." (PMID 24959222, 2014). "We provide evidence that COUP-TFI increases the motility of MCF-7 ERα-positive breast cancer cells by acting on CXCL12/CXCR4 signaling as an endogenous target." (PMID 24906407, 2014). "CXCR4 has been identified as an important chemokine receptor in regulating cell migration, invasion and metastasis in breast cancer." (PMID 24917186, 2014). "Chemokine (C-X-C motif) receptor 4 (CXCR4) has been found to closely correlate with the incidence, development, treatment and prognosis of breast cancer." (PMID 24959222, 2014). "Further evidence indicates that CXCR4 not only affects breast cancer metastasis but also promotes the survival and proliferation of breast cancer cells through increasing the number of blood vessels in tumors." (PMID 24475985, 2014). "It was identified that breast cancer cells express CXCR4 highly and that the ligand of CXCR4, CXCL12, is primarily expressed in the lungs, liver and bone marrow." (PMID 24932250, 2014). "In conclusion, tranilast affects CXCL12/ CXCR4 axis that lead to suppress invasion of breast cancer cells." (PMID 25237365, 2014). "The importance of CXCR4 axis in cancer is demonstrated by the fact that treatment of mice with CXCR4 antagonist leads to inhibition of metastasis of breast cancer." (PMID 24659999, 2014). "CXCL12 itself stimulates the tumor growth directly, via the CXC-chemokine receptor 4 (CXCR4), expressed among others on human breast carcinoma cells." (PMID 25254213, 2014). "Recently, many studies have shown that the presence of CXCR4 can signify invasion and metastasis in several cancers, including breast cancer." (PMID 24475985, 2014).
breast carcinoma (continued). "A previous cohort study indicated that the detection of CXCR4 expression is of great value in predicting the bone metastasis of breast cancer." (PMID 24959222, 2014). "To address this issue, we conducted a meta-analysis aimed at evaluating the value of CXCR4 as a prognostic marker for breast cancer and to determine the relationship between CXCR4 and several clinicopathological features of breast cancer." (PMID 24475985, 2014). "JWH-O15 inhibits hormone sensitive breast cancer metastasis by modulating CXCL12/CXCR4 signaling axis." (PMID 25115386, 2014). "They demonstrated that CXCR4 expressing breast cancer cells preferentially migrated towards protein extracts of the lung, which expresses CXCL12 abundantly." (PMID 24390633, 2014). "Blocking CXCR4 expression at the mRNA level by a combination of two siRNAs impairs invasion of breast cancer cells in the Matrigel invasion assay and inhibits breast cancer metastasis in an animal model." (PMID 24647809, 2014). "Knockdown of CXCR4 with RNAi impaired invasion of breast cancer cells and significantly limited the growth and metastasis to the liver and lung in vivo." (PMID 24647809, 2014). "Rhodes and colleagues investigated miRNA expression induced by the SDF-1/CXCR4 system in estrogen receptor-alpha-positive breast cancer cells." (PMID 25536052, 2014). "The construction of in vivo models of breast cancer metastasis to the bone further confirmed the inhibition of bone metastasis as a result of CXCR4 interference and the involvement of CXCR4/PI3K/AKT/MMP-9 signaling in bone metastasis." (PMID 24959222, 2014). "The correlation between CXCR4 expression and clinicopathological features and breast cancer prognosis was analyzed." (PMID 24475985, 2014). "Since breast cancer cells are an important target, we examined the expression of CXCR4 and CXCR7 in various cell lines and selected MCF-7 cancer cells as a representative that expresses both receptors at comparable levels but not CXCR3." (PMID 24770893, 2014). "The aim of the present study was to investigate the effects of CXCR4 on bone metastasis in breast cancer and to explore the mechanisms of this process." (PMID 24959222, 2014). "A meta-analysis based on published studies was performed with the aim of obtaining an accurate evaluation of the relationship between CXCR4 expression and the prognosis of breast cancer." (PMID 24475985, 2014). "CXCR4 drives the metastatic phenotype in breast cancer through induction of CXCR2, and activation of MEK and PI3K pathways." (PMID 24524196, 2014). "In breast cancer, high CXCR4 expression is found in aggressive tumours, correlating with poor prognosis and a decrease in disease-free survival." (PMID 24583601, 2014). "Inhibition of the CXCL12/CXCR4 interaction by neutralizing antibody significantly impairs metastasis of breast cancer cells to regional lymph nodes and lung." (PMID 24915301, 2014). "In the present study, we investigated CXCL12 and CXCR4 expression in breast cancer and further to analyze its role in survival and invasive ability of breast cancer cells." (PMID 24810923, 2014). "The role of CXCR4 and its unique ligand SDF-1α has been investigated in organ-specific metastases of several types of cancer, including breast cancer, and hypoxia increased the metastatic ability of breast cancer cells via upregulation of CXCR4." (PMID 24618817, 2014). "In an initial experiment, we investigated the expression of the chemokine receptors CXCR7 and CXCR4 in various breast cancer and other tumor cell lines by quantitative RT-PCR and Western blots." (PMID 24770893, 2014). "The observations revealed that CXCR4 siRNA significantly inhibits the proliferation and invasion of breast cancer cells." (PMID 24959222, 2014). "It was also noted that COUP-TFI disturbs the estrogenic regulation of CXCL12 and CXCR4 in MCF-7 cells, supporting the idea that COUP-TFI leads to a loss of E2 dependency in breast cancer cells." (PMID 24906407, 2014).
breast carcinoma (continued). "The intracellular expression of chemokine receptors, in other tumors, has been shown to be correlated with metastasis directed to lymph nodes and with a bad prognosis (e.g., CXCR4 in breast cancer; in lung cancer; in colon cancer)." (PMID 24559071, 2014). "The data show an average 6-fold higher CXCR4 expression in patient-derived breast cancer stem cells (n=14, p<0.01)." (PMID 24583601, 2014). "CXCR4 is upregulated in metastatic breast cancer cell lines and lymph node metastasis, and cells expressing CXCR4 predominantly migrate to tissues that express the ligand CXCL12." (PMID 25254213, 2014). "It suggested that the chemokine CXCL12 and its sole ligand CXCR4 played important role in the malignant of breast cancer." (PMID 24810923, 2014). "In conclusion, the preliminary in vitro experiment revealed that the proliferation and invasion of breast cancer cells is inhibited with the interference of CXCR4." (PMID 24959222, 2014). "In the present study, the effect of CXCR4 on the bone metastasis of breast cancer by targeting the downregulation of CXCR4 using RNAi techniques was observed." (PMID 24959222, 2014). "As an example, CXCR4 is a well-characterized bone marrow homing receptor expressed by T cells; research has found that both prostate cancers and breast cancers that metastasize to the bone commonly express CXCR4." (PMID 25368611, 2014). "In this regard, the role of the CXCL12/CXCR4 axis in breast cancer invasion and metastasis is widely studied." (PMID 24886617, 2014). "The results of immunohistochemistry demonstrated CXCR4 and CXCL12 co-expression in 27.4% (50/182) breast cancer samples and the co-expression of CXCR4 and CXCL12 correlated with lymph node metastasis and TNM stage (p < 0.01)." (PMID 24810923, 2014). "CXCR4 has previously been shown to be important in metastasis of breast cancer and is highly expressed in the cancer stem cell population of other epithelial cancers." (PMID 24583601, 2014). "In breast cancer, CXCR4 signalling has been reported to be a mediator of metastasis, and is linked to poor prognosis." (PMID 24583601, 2014). "Firstly, the CCK-8 cell proliferation and Transwell chamber assays were used to detect the oncological characteristics of the breast cancer cells prior to and following CXCR4 suppression." (PMID 24959222, 2014). "As a result, the onset of the bone metastasis of breast cancer cells was prolonged and the metastasis was attenuated with the interference of CXCR4, which tentatively confirmed that CXCR4 RNAi inhibits the spread of breast cancer cells to the bone." (PMID 24959222, 2014). "The chemokine CXCL12 (stromal cell-derived factor-1, SDF-1) and its receptor CXCR4 play a major role in tumor initiation, promotion, progression and metastasis, especially for breast cancer cells." (PMID 24770893, 2014). "CXCR4 small interfering RNA was transfected into the breast cancer cell line, MDA-MB-231BA-rfp, and the cell proliferation and invasion abilities of the cells were measured using cell counting kit-8 cell proliferation and Transwell assays." (PMID 24959222, 2014). "In conclusion, the present study demonstrated that CXCR4 RNAi inhibits bone metastasis and the cell proliferation and invasion abilities of breast cancer cells." (PMID 24959222, 2014). "Based on the results of the in vitro experiment, an in vivo experiment was conducted to investigate the effect of CXCR4 inhibition on breast cancer bone metastasis." (PMID 24959222, 2014). "The chemokine receptor CXCR4 plays a significant role in biological processes, as well as in tumorigenesis and the progression of cancer, especially breast cancer." (PMID 24475985, 2014). "The insulin-like growth factor 1 tyrosine kinase receptor (IGF-1R) and the chemokine G-protein coupled receptor, CXCR4 have been shown to play an important role in breast cancer metastasis." (PMID 23320409, 2013).